USP2 (ubiquitin specific peptidase 2)
Diseases named in the same sentence as USP2 in open-access papers (continued):
Sharing a sentence is not in itself a finding about the gene and the disease.
tumor (continued). "In addition to evaluation of these drugs for anti-tumor therapy, these drugs could also be tested as treatments for other diseases where the pathology includes contributions from USP2." (PMID 33530560, 2021). "Additionally, ESR1, OTUD6B, USP2, and USP37 showed a positive correlation with risk scores, while USP22 exhibited a significant negative correlation with risk scores (r = -0.7, p < 0.0001), suggesting a potential role for these genes in ESCC tumor progression and patient prognosis." (PMID 39742278, 2024). "As both mechanisms serve to reduce PD-L1 levels, the USP2-VPRBP axis should suppress PD-L1-mediated immune evasion and thereby enhance tumor immunosurveillance." (PMID 37024504, 2023). "At the same time, USP2 stabilizes the E2F4 protein through deubiquitination, reducing its transactivation in tumor cells and thereby inhibiting its protective autophagy." (PMID 36611139, 2023). "A prognostic index for tumor samples could be calculated by the formula: IRGPI = (HTN3 expression * 0.096) + (CTSG expression * −0.152) + (MAPT expression * 0.122) + (CCL28 expression * −0.094) + (PTX3 expression * 0.138) + (SEMA3G expression * −0.140) + (USP2 expression * 0.107)." (PMID 36845378, 2023). "Therefore, the exact roles of USP2 in tumor pathogenesis could be complex and tumor-type-dependent." (PMID 36567903, 2022). "Accordingly, a selective USP2 inhibitor, ML364, has been shown to effectively suppress tumor metastasis in mice." (PMID 33530560, 2021). "Depletion of several ubiquitinases and proteasome components (DTX3L, UBE2E1, RNF31, RNF115, USP2, USP42, PSMC3, and PSMD10) were also found to inhibit tumor cell migration." (PMID 31278301, 2019). "They found higher degree of methylation of MGMT, RARβ, RASSF1A, and CDH13 in tumour specimens and of SOCS-1 in peripheral blood with higher levels of IL-6, while others found less degree of methylation of USP2, TMEM49, SMAD3, DTNB, and IL-6 promoter with higher levels of IL-6." (PMID 31205673, 2019). "Hematoxylin and eosin (H&E) staining identified an increase in tumor cells in the VCP-overexpressing group, while the immunohistochemical (IHC) analysis showed that in the VCP gene activation group, the expression of FASN, VCP, and USP2 in tumor cells was relatively increased." (PMID 39489738, 2024). "We observed that USP2 is primarily expressed in tumor cells but not in the stroma." (PMID 30918246, 2019). "However, if USP2 could affect tumor progression through targeting ARID2 has not been reported." (PMID 36567903, 2022). "Indeed, synergistic effects induced by the combination of a small-molecule USP2 inhibitor and anti-PD1 monoclonal antibody were also readily reproduced in the RM-1 tumor-bearing C57BL/6 mice without any obvious toxicity." (PMID 37024504, 2023).
infection (7 papers, 2013 to 2023). The state of being infected such as from the introduction of a foreign agent such as serum, vaccine, antigenic substance or organism. "Correspondingly, infection with an adenovirus encoding Usp2 shRNA significantly lowered blood glucose, blood insulin, hepatic glycogen content, and insulin sensitivity in high fat diet–fed mice, suggesting that USP2 plays a role in aggravating T2DM pathogenesis." (PMID 36834633, 2023). "In addition to modulating the downstream signaling of the IFN receptors, USP2 has also been postulated to alter the production of IFN type I. Infection with SeV caused a small decrease in the levels of both USP2-1 and USP2-4 in HEK293 cells and macrophage-like THP-1 cells." (PMID 33530560, 2021). "Little is known about these USPs, but transcriptional upregulation and high Usp2 protein levels have been reported for two different mouse models of infection." (PMID 26195599, 2016). "We found a set of three ubiquitin specific proteases regulating immune signals in response to infections, among which USP2 controls the homeostasis of an essential signalling component -named Imd- by promoting its degradation at the proteasome." (PMID 25027767, 2014). "Enhanced activation of Dpt and AttA in Usp2-silenced flies was similarly observed at several time-points from 3 to 9 hours following infection." (PMID 25027767, 2014). "Overexpression of USP2 in the heart was conducted by AAV9 infection." (PMID 32963492, 2020). "Genes that were down-regulated genes at 24h post infection included inflammatory and anti-pathogen genes (CSF1 and USP2) and the cell apoptosis and death genes (MICB, BUB1B, ITGB2, UBB and BIRC3)." (PMID 23527143, 2013). "The D. melanogaster ubiquitin-specific protease 36 (USP36) and USP2 negatively regulate the IMD pathway after infection by Gram-negative pathogens." (PMID 36537797, 2023).
metabolic disorders (3 papers, 2021 to 2026). "Along with cell culture models, mouse models induced using chemical blockers and gene engineering have substantially contributed to our knowledge of the crucial roles of USP2 in energy metabolism and metabolic disorders." (PMID 42072324, 2026). "Thus, the impact of USP2 on metabolic disorders seems to be dependent on the cell types expressing it." (PMID 36834633, 2023). "Usp2 deficiency–induced subfertility can thus be regarded as a metabolic disorder in a broader sense of the term, although it does not manifest as a disruption of energy metabolism at the individual level." (PMID 36834633, 2023). "Interestingly, ROS-induced mitochondrial dysfunction is attributable to metabolic disorders at the individual level, suggesting that USP2 might affect energy consumption more broadly." (PMID 36834633, 2023).
adenocarcinoma (1 paper, 2022). A common cancer characterized by the presence of malignant glandular cells. "Results indicated that both paired and unpaired LSCC and adenocarcinoma tissues demonstrated a significantly lower level of USP2 mRNA expression, compared with NT." (PMID 36567903, 2022).
bacterial infection (1 paper, 2014). "Therefore, when overexpressed in vivo, USP2 and USP34 behave as negative regulators of the fly immune response to bacterial infections." (PMID 25027767, 2014).
hematologic disorder (1 paper, 2023). A disease involving the hematopoietic system. "In contrast, upon the treatment with the USP2 inhibitor ML364, no obvious signs of hematologic disorder or microscopic tissue damage were observed." (PMID 37024504, 2023).
intestinal diseases (1 paper, 2022). "This study adds new evidence to support the relationship between circadian rhythm and intestinal diseases and proposes the potential role of USP2 in intestinal diseases, thereby providing a target for subsequent molecular interventions." (PMID 36172047, 2022).
USP2 also shares sentences with these, for which no sentence is quoted: hepatocellular carcinoma (3 papers); acute leukemia (1); acute promyelocytic leukemia (1); Alzheimer disease (1); bipolar disorder (1); bladder cancer (1); central nervous system disease (1); Cerebellar atrophy (1); cervical cancer (1); cholestasis (1); choroidal melanoma (1); diabetic foot ulcers (1); familial cylindromatosis (1); heart failure (1); hemophilia (1); Hypercalciuria (1); liver disease (1); lung squamous cell carcinoma (1); metastatic tumor (1); multiple myeloma (1); neuroblastoma (1); non-Hodgkin lymphoma (1); oral squamous cell carcinoma (1); ovarian tumor (1); psychosis (1); renal carcinoma (1); rheumatoid arthritis (1); schizophrenia (1).